TRPM7 (transient receptor potential cation channel subfamily M member 7)
Diseases named in the same sentence as TRPM7 in open-access papers (continued):
Sharing a sentence is not in itself a finding about the gene and the disease.
atrial fibrillation (continued). "A recent study has demonstrated that TRPM7 channels are expressed in human atrial fibroblasts, which mediate Ca2+ signals and confer fibrogenesis in humans with atrial fibrillation." (PMID 22802050, 2012). "Transient receptor potential melastatin-7 (TRPM7) channels have been recently reported in human atrial fibroblasts and are believed to mediate fibrogenesis in human atrial fibrillation." (PMID 22802050, 2012). "Our results demonstrate for the first time that functional TRPM7 channels are present in human atrial myocytes, and the channel expression is upregulated in the atria with atrial fibrillation." (PMID 22802050, 2012). "TRPM7 activation in human atrial fibroblasts leads to fibrogenesis and atrial fibrillation." (PMID 34445449, 2021). "Additionally, the variability of the TRPM7 current density in human right atrial cardiomyocytes is related to the clinical history, being higher in disease conditions such as atrial fibrillation and in ischemic heart disease." (PMID 34445449, 2021). "The second aim was to determine whether pre-existing pathological conditions such as atrial fibrillation and/or ischemic heart disease could alter the properties or the expression of the TRPM7 current." (PMID 28129376, 2017). "Finally, the fact that two of the patients in our study also suffered from paroxysmal atrial fibrillation promotes TRPM7 as a novel candidate interfering with conductance in cardiac cells." (PMID 27020697, 2016). "Here we report that impaired channel function but not kinase activity of TRPM7 in MKs causes macrothrombocytopenia in Trpm7fl/fl-Pf4Cre mice and likely in several members of a human pedigree, which, in addition, feature atrial fibrillation." (PMID 27020697, 2016). "TRPM7 has been found to be involved in a number of human diseases and pathological conditions, including the activation of immune system cells, brain ischemia, Guamanian lateral sclerosis and Parkinson's, atrial fibrillation, and cancer." (PMID 24710004, 2014). "More effort is required to clarify whether and how TRPM7 channels in atrial myocytes mediate the initiation and/or maintenance of atrial fibrillation." (PMID 22802050, 2012). "This indicates an increase of TRPM7 current in human atrial fibrillation." (PMID 22802050, 2012). "Moreover, TRPM-7 mediated Ca2+ signals have been shown to play an essential role for atrial fibroblasts leading to fibrosis that could eventually result in atrial fibrillation." (PMID 33371897, 2020). "In the adult, TRPM7 in the sinoatrial node is required to maintain automaticity, and its importance in cardiac electrophysiology is further highlighted by work showing upregulation of TRPM7 in fibroblasts from patients with atrial fibrillation, an effect that may contribute to fibrogenesis." (PMID 25692682, 2015). "Therefore, enhanced TRPM7 channels may also participate in the higher propensity to delayed afterdepolarization-mediated ectopic activity in patients with chronic atrial fibrillation." (PMID 22802050, 2012). "A recent study has reported that TRPM7 channel gene expression is remarkably increased in fibroblasts isolated from human atria of patients with atrial fibrillation, it is, therefore, believed that TRPM7-mediated Ca2+ signals may mediate fibrogenesis in human atrial fibrillation." (PMID 22802050, 2012). "It has been shown that transient receptor potential melastatin 7 (TRPM7) is the main Ca2+-permeable channel involved in the TGF-β1-induced activation of human atrial fibroblasts into myofibroblasts, promoting atrial fibrillation." (PMID 24710004, 2014). "Interestingly, we found that the TRPM7 current could be already detectable immediately upon membrane patch break-in in freshly isolated human cardiomyocytes from atrial tissues of patients with sinus rhythm, as also observed by others in tissues from patients with atrial fibrillation." (PMID 28129376, 2017). "TRPM7, but not TRPM4, is upregulated in atria of individuals with atrial fibrillation." (PMID 22802050, 2012).
atrial fibrillation (continued). "Interestingly, TRPM7, but not TRPM4, is markedly upregulated in human atria from patients with atrial fibrillation." (PMID 22802050, 2012).
Hypertension (19 papers, 2015 to 2025). The presence of chronic increased pressure in the systemic arterial system. "TRPM7-regulated magnesium influx affects endothelial function, inflammatory response and vascular integrity that underlie hypertension." (PMID 31219801, 2019). "In the recent decade, TRPM7-mediated magnesium influx has been shown to affect cellular activities implicated in hypertension, such as endothelial dysfunction and vascular integrity maintenance." (PMID 31219801, 2019). "The mechano-sensitivity of TRPM7 might be implicated in hypertension, since molecular TRPM7 expression in vascular smooth muscle cells was found to be decreased in spontaneously hypertensive rats." (PMID 37842082, 2023). "Although TRPM7 has been implicated in vascular pathological changes that underlie hypertension, whether it is associated with PAH pathogenesis remains unknown." (PMID 31219801, 2019). "Considering the relationship between aldosterone, TRPM7, and cellular Mg2+ homeostasis we questioned whether aldosterone-induced cardiovascular and renal injury, hypertension, and perturbed electrolyte homeostasis involve TRPM7, by studying TRPM7-deficient mice (TRPM7+/Δkinase)." (PMID 35882956, 2022). "Using mice heterozygous for the truncation mutation in TRPM7 (TRPM7+/Δkinase), we demonstrated that TRPM7 deficiency is associated with cardiovascular inflammation and fibrosis and increased susceptibility to Ang II-induced endothelial dysfunction and hypertension." (PMID 32706027, 2020). "By increasing the methylation of the TRPM7 promoter, leptin receptor-deficient mice and leptin-deficient mice can reduce Trpm7 transcription and expression, demonstrating how the TRPM7 channel contributes to leptin-induced hypertension." (PMID 38255767, 2024). "Direct evidence supporting TRPM7 involvement in the development of hypertension was first demonstrated in Ang II-induced hypertension, where the development of hypertension was amplified in TRPM7-deficent mice." (PMID 36818331, 2023). "On the other hand, it was shown that TRPM7 inhibition by pharmacologic agents reduced hypertension induced by leptin." (PMID 36818331, 2023). "Here we advance the notion and show that TRPM7+/Δkinase mice are more sensitive to blood pressure-elevating effects of aldosterone than WT mice, which only develop hypertension when salt is added." (PMID 35882956, 2022). "We also demonstrated that Ang II-infused TRPM7+/Δkinase mice have severe hypertension and reduced activation of the TRPM7-kinase target proteins annexin-A1 and calpain II44." (PMID 35882956, 2022). "Leptin interacts with CB via receptor potential melastatin 7 (TRPM7) channel and the up-regulation of leptin-TRPM7 axis in CB augments hypoxic ventilatory response hypertension." (PMID 34201760, 2021). "Our group proposed that CB induces hypertension by the stimulation of leptin signaling in the glomus cells, and the downstream activation of transient receptor potential melastatin 7 (TRPM7) channels." (PMID 32698380, 2020). "TRPM6 and TRPM7 were both found in the vascular smooth muscle cells and were shown to regulate hypertension via Mg2+ homeostasis." (PMID 29206233, 2017). "One member of the vanilloid TRP family, TRPV1, mediates the sensing of the carotid body to Th2 cytokines and lysophosphatidic acid, and a member of the melastatin TRP family, TRPM7, is involved in the regulation of obesity-induced hypertension mediated by leptin." (PMID 41226725, 2025). "Thus, leptin induces hypertension by acting also in the carotid bodies, which opens the perspective for TRPM7 blockers as a potential therapy in obesity-related hypertension." (PMID 38186879, 2024). "Obesity‐induced hyperleptinemia may lead to histone acetylation and methylation of Trpm7, thereby promoting hypertension through upregulating Trpm7 expression." (PMID 38405061, 2024).
Hypertension (continued). "Furthermore, after the local application of TRPM7 blocker FTY720 or TRPM7 shRNA in CB, it was found that it inhibited leptin-induced hypertension effectively." (PMID 38255767, 2024). "TRPM7 is a cation channel that regulates transmembrane Mg2+ and Ca2+ and is involved in a variety of (patho)physiological processes in the cardiovascular system, contributing to hypertension, cardiac fibrosis, inflammation, and atrial arrhythmias." (PMID 36818331, 2023). "Furthermore, the upregulated TRPM7 function has been observed in patients with ischemia-reperfusion, arrhythmias, and hypertension." (PMID 37764704, 2023). "The negative relationship between TRPM7 and blood pressure was previously highlighted in various models of hypertension, where we found decreased TRPM7 expression in cardiovascular and renal tissues from spontaneously hypertensive rats and in Ang II and aldosterone-treated mice." (PMID 35882956, 2022). "Fortunately, epigenetic changes are reversible, and epigenetic modifications targeting TRPM7 may serve as a novel therapeutic approach for the treatment of obese hypertension." (PMID 35573736, 2022). "In addition, levels of leptin are higher in obese individuals than in lean ones, leptin can induce hypertension by enhancing TRPM7 channel expression in the carotid body glomus cells and increasing TRPM7 activity." (PMID 33716794, 2021). "But the specific contribution of TRPM7 to hypertension is still ambiguous." (PMID 31219801, 2019). "There is a growing body of evidence in the literature highlighting the involvement of TRP channels, including TRPM7/8, TRPV1, and TRPA1, in the pathophysiology of hypertension." (PMID 38255767, 2024). "In addition, TRPM7 might contribute to hypertension via its Mg2+ permeability." (PMID 36818331, 2023). "Hypertension and CB chemoreflex), we have also shown that leptin stimulates CB glomus cells and augments CSN activity through TRPM7 channels, elevating blood pressure." (PMID 32698380, 2020). "One member of the TRP subfamilies, the Transient Receptor Potential cation channel, subfamily M, member 7, also known as TRPM7, is ubiquitously expressed, possesses a kinase domain, and potentially has a role in hypertension control in vascular systems." (PMID 25946314, 2015). "Hypertension in both models was abolished by bilateral CSN resection and the blockade of TRPM7 signaling, either by the administration of a nonspecific TRPM7 blocker, FTY720, or by a viral vector containing short hairpin RNA." (PMID 32698380, 2020).
bladder cancer (18 papers, 2015 to 2025). "TRPM7 was also overexpressed in human bladder cancer tissue and this increased expression was associated with tumor recurrence, metastasis and poor prognosis." (PMID 38255793, 2024). "TRPM7 is also highly expressed in bladder cancer tissues and cell lines, and it is associated with poor clinical outcomes because it is involved in cell proliferation, migration and invasion." (PMID 37762011, 2023). "Oridonin exhibited outstanding antiproliferative and antimigratory effects on bladder cancer, and these effects were at least partially associated with targeting of TRPM7 through inactivation of the ERK and AKT signaling pathways." (PMID 34285910, 2021). "TRPM7 is also associated with bladder cancer, such that TRPM7 mRNA and protein expression are higher in bladder tumor tissue compared to adjacent non-tumoral tissue, and elevated TRPM7 expression correlates with recurrence, metastasis and a poorer prognosis for this disease." (PMID 31275168, 2019). "Accordingly, there was a suppression of TRPM7 expression, accompanied by an induction of apoptosis and inhibition of the advancement and spread of bladder cancer." (PMID 41325388, 2025). "TRPM7 silencing is dependent on calcium signaling to activate the ERK1/2 pathway, thereby causing apoptosis in bladder cancer cells." (PMID 39633507, 2024). "TRPM7 knockdown by siRNA revealed that TRPM7 promoted bladder cancer cell proliferation, migration and invasion." (PMID 38255793, 2024). "In human urinary bladder cancer (BCa) cells, apoptotic cell death was observed, in vitro, to be facilitated by TRPM7 knockdown." (PMID 37842082, 2023). "In this study, injection of antitumor carvacrol was found to reduce TRPM7 activity, thereby suppressing tumor growth in the mouse bladder cancer in vivo." (PMID 37842082, 2023). "Gene knockout is believed to be more reproducible, prompting us to make a TRPM7 knockout (hereafter referred to as TRPM7KO) human urinary bladder carcinoma cell line (T24 cell) using the CRISPR/Cas9 technology." (PMID 36878949, 2023). "It has also been shown that TRPM7 was able to regulate G1-S transition in retinoblastoma cells and bladder cancer cells." (PMID 35883700, 2022). "Consistent with this, the TRPM7 knockdown decreases the migration and invasion of bladder cancer cells in vitro." (PMID 31275168, 2019). "Other pathways regulated by TRPM7 in bladder cancer cells are the Src, Akt and JNK pathways." (PMID 37762011, 2023). "In conclusion, downregulated TRPM7 could reduce the activity of bladder cancer cells and induce cell apoptosis via ERK1/2 pathway." (PMID 27662662, 2016). "Therefore, we hypothesized that TRPM7, which is involved in the calcium signaling pathway, could affect bladder cancer by the MAPK signaling pathway to trigger BCa cell cycle arrest and apoptosis." (PMID 27662662, 2016). "TRPM7 has been reported to regulate tumor growth, migration and invasion via the Src, Akt and c-Jun N-terminal kinase (JNK) signaling pathway in human bladder cancer cell lines." (PMID 38255793, 2024). "The present study aims to investigate the effect and mechanism of TRPM7, an important TRPM family member involved in Ca2+-permeable channel, on human bladder cancer, which remains largely unknown yet." (PMID 27662662, 2016). "After its MCT1- and NHE1-directed entry in oncogenic H-Ras-transformed bladder cancer cells, 3-BrPA activates the PARP and RIPK3/MLKL/Drp1 necrotic axes, presumably together with the RIPK3/MLKL/TRPM7, RIPK3/MLKL/NHE1 and RIPK3/SAPK/JNK necrotic subroutines, in RIPK1-independent manner." (PMID 26198749, 2015). "TRPM7 has been reported to be expressed in human and mouse urothelium, as well as in MBT-2 mouse bladder cancer cells and T24 human bladder cancer cells, but its effect and mechanism in human bladder cancer remain largely unknown." (PMID 27662662, 2016).
bladder cancer (continued). "Downregulation of TRPM7 is known to play an important role in bladder cancer cell apoptosis 21,22 and TRPV2 is known to enhance bladder cancer cell migration and invasion but not cell proliferation." (PMID 35919815, 2022).
gastric cancer (18 papers, 2011 to 2025). A primary or metastatic malignant neoplasm involving the stomach. "5-lipoxygenase inhibitors, waixenicin A and quercetin have been also demonstrated to decrease the TRPM7 channel function and cause the death of gastric cancer cells." (PMID 38255793, 2024). "The role of the TRPM7 channel in the pathophysiology of gastric cancer has been repeatedly demonstrated." (PMID 38255793, 2024). "A recent study has revealed that high TRPM7 expression is closely related to aggressive tumor behavior and an advanced stage, and was an indicator of poor prognosis in human gastric cancer." (PMID 38255793, 2024). "Multiple TRPM7 inhibitors have been developed and applied in animal models, positioning TRPM7 as a promising target for gastric cancer treatment." (PMID 38370477, 2024). "By integrating gene-silencing techniques targeting B7H6 with the potential regulatory effects on TRPC6 and TRPM7, we aim to explore a novel approach to overcoming drug resistance in gastric cancer therapy." (PMID 39768254, 2024). "Inhibition of TRPM7 has also shown promising results, as it significantly reduces gastric cancer cell proliferation and promotes apoptosis." (PMID 38370477, 2024). "Recent studies have highlighted the role of transient receptor potential (TRP) ion channels, particularly TRPC6 and TRPM7, in the progression and metastasis of various cancers, including gastric cancer." (PMID 39768254, 2024). "It is worth noting that TRPC6 and TRPM7 ion channels are also known to play roles in gastric cancer progression." (PMID 39768254, 2024). "In this study, it was aimed at investigating the effect of TRPM7 expression on prognosis in gastric cancer patients." (PMID 34938330, 2021). "AGS gastric cancer cells exhibit TRPM7-like currents, and suppression of these currents by the unspecific TRPM7 inhibitors, La3+ or 2-APB, resulted in a decrease in cell viability and higher apoptosis rates." (PMID 32182937, 2020). "Functional analysis of TRIM28, EIF4A2, NAP1L1, PLD3, RPL18A, and TRPM7 suggested that they play direct roles in gastric cancer." (PMID 27835598, 2016). "- Required for cell survival involving Mg2+. - Waixenicin A, TRPM7 blocker, inhibits growth andsurvival of gastric cancer cells AGS. - Involved in ginsenoside Rd-induced apoptosis AGS cells." (PMID 25079291, 2014). "Chemical inhibitors of TRPM7 channel activity have been shown to produce gastric cancer cells death and anti-proliferative effects in pancreatic adenocarcinoma cells." (PMID 25079291, 2014). "Ultimately, based on these results, it has been claimed that TRPM7 expression may play an important role in survival in patients with gastric cancer." (PMID 34938330, 2021). "Furthermore, lncRNA SNHG8 modulated several functional genes, including TRIM28, NAP1L1 and TRPM7 which affected downstream cancer pathways in gastric cancer." (PMID 30299268, 2018). "Ionotropic receptors such as TRPM7 and TRPV1 are known to be involved in gastric cancer through the PLC/RAS/ERK pathway or through calcium loading via ERK/P38/JNK, activating cell proliferation or cell death." (PMID 40076652, 2025). "In gastric cancer, TRPC6 and TRPM7 have been shown to influence oncogenic processes through modulation of intracellular calcium levels, which is critical for tumor progression." (PMID 39768254, 2024). "Firstly, we selected human gastric cancer tissues and adjacent tissues, and detected the expression of OIP5-AS1 by qRT-PCR, and detected CD147 and TRPM7 by IHC." (PMID 38156103, 2023). "TRPM7 is essential for the survival of AGS cells 26, 27, and TRPM2 has the ability to control the invasion of gastric cancer cells." (PMID 33859522, 2021). "In gastric cancer (TCGA-STAD dataset), we observed a mild positive correlation of TRPM7 with TRPM6, MAGT1, CNNM3 and CNNM4 (=0.1< R < 0.22)." (PMID 33450887, 2021).
gastric cancer (continued). "The ability of TRPM7 channel blockade to inhibit the growth and survival of AGS cells suggests TRPM7 to be a potential target for the treatment of gastric cancer." (PMID 21420431, 2011). "Notably, six TRP channels (TRPC6, TRPM2, TRPM5, TRPM7, TRPV4, and TRPV6) have been identified as crucial players in the growth and survival of gastric cancer." (PMID 38370477, 2024). "However, there are no comprehensive clinical studies about the effect of TRPM7 expression on gastric cancer (GC) prognosis." (PMID 34938330, 2021).